TNFAIP1 (TNF alpha induced protein 1)
Description:
Substrate-specific adapter of a BCR (BTB-CUL3-RBX1) E3 ubiquitin-protein ligase complex involved in regulation of cytoskeleton structure. The BCR(TNFAIP1) E3 ubiquitin ligase complex mediates the ubiquitination of RHOA, leading to its degradation by the proteasome, thereby regulating the actin cytoskeleton and cell migration. Its interaction with RHOB may regulate apoptosis. May enhance the PCNA-dependent DNA polymerase delta activity.
Synonyms: hBACURD2; EDP1; B61; B12; MGC2317; BTBD34
Tractability: PROTAC: ubiquitination databases record sites on it.
Gene: Protein-coding gene on chromosome 17 (28,335,602 to 28,347,009, forward strand). Ensembl gene ENSG00000109079.
Subcellular location: Cytoplasm; Nucleus; Endosome
Subcellular location (Human Protein Atlas): Nucleoli
Pathways (Reactome):
Signal Transduction: RND2 GTPase cycle; RND3 GTPase cycle
Gene Ontology:
Molecular function: identical protein binding; protein binding; small GTPase binding; ubiquitin-like ligase-substrate adaptor activity; ubiquitin-protein transferase activity; cyclin binding
Biological process: cell migration; immune response; negative regulation of Rho protein signal transduction; proteasome-mediated ubiquitin-dependent protein catabolic process; protein ubiquitination; stress fiber assembly; apoptotic process; positive regulation of DNA replication; protein homooligomerization; ubiquitin-dependent protein catabolic process
Cellular component: Cul3-RING ubiquitin ligase complex; cytoplasm; endosome; cytosol; nucleus
Genetic constraint (gnomAD): Loss-of-function variants: 20 observed, 32.28 expected, observed/expected ratio (o/e) 0.62, 90% interval 0.44 to 0.9. The upper end of that interval is the gene's LOEUF score, 0.9, which puts it in group 3 of 6, group 1 being the genes least tolerant of losing a copy. Missense variants: 319 observed, 433.49 expected, observed/expected ratio (o/e) 0.74, 90% interval 0.67 to 0.81. Synonymous variants: 166 observed, 171.62 expected, observed/expected ratio (o/e) 0.97, 90% interval 0.85 to 1.1.
Homologues: Orthologues: macaque TNFAIP1 (100% identical), chimpanzee TNFAIP1 (99% identical), pig TNFAIP1 (99% identical), rabbit TNFAIP1 (99% identical), guinea pig TNFAIP1 (98% identical), mouse Tnfaip1 (97% identical), rat Tnfaip1 (96% identical), tropical clawed frog tnfaip1 (90% identical), zebrafish tnfaip1 (71% identical), Drosophila melanogaster CG10465 (59% identical), dog TNFAIP1 (59% identical), Caenorhabditis elegans D2045.8 (26% identical), and 28 more. Paralogues in human: KCTD10 (71% identical), KCTD13 (66% identical).
Diseases named in the same sentence as TNFAIP1 in open-access papers:
TNFAIP1 is named in the same sentence as 34 diseases in open-access papers, as found by Europe PMC text mining. Sharing a sentence is not in itself a finding about the gene and the disease. The quoted sentences say what the papers report.
lung carcinoma (8 papers, 2015 to 2023). "In human medicine, breast cancer, gastric carcinomas, and lung cancer are known to be associated with TNFAIP1 mutations." (PMID 37760246, 2023). "Taken together, these findings demonstrate that TNFAIP1 is overexpressed in human lung cancer and associated with reduced overall survival of patients." (PMID 32327643, 2020). "Finally, bioinformatics and clinical sample analyses revealed that BTBD9 was downregulated while TNFAIP1 was overexpressed in human lung cancer, which was associated with poor overall survival of patients." (PMID 32327643, 2020). "Cytoplasmic circ-0001320 is downregulated in lung cancer cells and inhibits the growth and invasion of lung cancer cells through the miR-558/TNFAIP1 and TPM1 pathways." (PMID 36338714, 2022). "In view of TNFAIP1 was highly expressed in many human cancer cells including lung cancer cells and osteosarcoma cells, and modulated tumorigenesis and cancer cell migration." (PMID 33553178, 2021). "Functionally, we found that BTBD9 suppressed lung cancer cell migration by promoting TNFAIP1 degradation in vitro." (PMID 32327643, 2020). "In contrast, TNFAIP1 was overexpressed in lung cancer, which predicted poor prognosis in lung cancer patients." (PMID 32327643, 2020). "For example, miRNA-17-5p inhibits proliferation and initiates apoptosis by targeting TGFβR2 in lung cancer; MiR-424 targets the oncogene TNFAIP1 and promotes metastasis in lung cancer." (PMID 32252678, 2020). "As such, downregulation of BTBD9 promoted lung cancer cell migration by upregulating the expression of TNFAIP1, whereas TNFAIP1 deletion abrogated this effect." (PMID 32327643, 2020). "To elucidate the molecular mechanism by which BTBD9 regulates TNFAIP1 to affect lung cancer cell migration, we detected the expression level of RhoA, which was reported to be regulated by TNFAIP1 and responsible for stress fiber formation." (PMID 32327643, 2020). "For example, CRL3BTBD9 degrades TNFAIP1 and further regulates lung cancer metastasis." (PMID 35064108, 2022). "We speculated that BTBD9 affected the expression of these proteins by modulating TNFAIP1 degradation and altering the metastatic ability of lung cancer cells." (PMID 32327643, 2020). "Finally, we clarified that TNFAIP1 is overexpressed in the development of lung cancer due to dysfunction of CRL3 adaptor protein BTBD9, which is also associated with poor prognosis in lung cancer patients." (PMID 32327643, 2020). "Our recent study demonstrated that miR-224 promotes lung cancer cell's migratory, invasive and proliferative capacity and in general tumor growth both in vitro and in vivo by direct targeting of SMAD4 and TNFAIP1." (PMID 26307684, 2015). "MiR-224 has been reported to be up-regulated in several solid tumors including hepatocellular carcinoma, colorectal cancer, breast cancer, and lung cancer, and repressing various targets such as API5, SMAD4, PHLPP1, PHLPP2, RKIP and TNFAIP1." (PMID 26307684, 2015). "Finally, as the specific adaptor of TNFAIP1, BTBD9 was found to be expressed at low levels in lung cancer, leading to the dysregulation of CRL3BTBD9 and subsequent upregulation of TNFAIP1." (PMID 32327643, 2020). "However, the silencing of neither BTBD9 nor TNFAIP1 affected cancer cell proliferation, and our study systematically demonstrated that the downregulation of BTBD9 halted TNFAIP1 degradation in lung cancer and subsequently drove lung cancer cell metastasis." (PMID 32327643, 2020).
breast carcinoma (5 papers, 2010 to 2023). "Survival analysis of a group of 410 breast cancer patients revealed significant survival-associated individual genes and gene pairs in the TNFAIP1/POLDIP2 CSAGA." (PMID 20158880, 2010). "The TNFAIP1/POLDIP2 CSAGA is a clinically relevant transcriptional structural-functional gene module linked to erb-b2 receptor tyrosine kinase 2 (ERBB2) amplicon core gene expression in breast cancer and connected with amplification of the genomic region on 17q11.2." (PMID 36425112, 2022). "The role of Poldip2 in tumor formation is not well known yet, although a study of the sense-antisense gene pair of TNFAIP1/POLDIP2 found poor prognosis in breast cancer patients with upregulated Poldip2 expression." (PMID 24797518, 2014). "TNFAIP1/POLDIP2 CSAGA maps the risks of breast cancer relapse onto the complex genomic locus on 17q11.2." (PMID 20158880, 2010). "Correlation analysis of the TNFAIP1/POLDIP2 SFGM in four grades of breast cancer (G1, G1-like, G3-like and G3) revealed a strengthening of the correlations between the genes of the TNFAIP1/POLDIP2 SFGM." (PMID 20158880, 2010). "Finally, direct and independent evidence of the TNFAIP1/POLDIP2 SFGM activation in breast cancer cells comes from the custom track for RNA polymerase II binding in the MCF7 breast cancer cell line (black arrows)." (PMID 20158880, 2010). "It is important to note that the TNFAIP1/POLDIP2 module is located outside of the well-known ERBB2 amplicon on 17q12, over-representation of which in the genome is often associated with the occurrence of the ERBB2-positive breast cancer subtype." (PMID 20158880, 2010). "We analyzed the TNFAIP1/POLDIP2 CSAGA on 17q11.2 in two breast cancer cohorts." (PMID 20158880, 2010). "We suggest that the TNFAIP1/POLDIP2 CSAGA represents a clinically significant transcriptional structural-functional gene module associated with amplification of the genomic region on 17q11.2 and correlated with expression ERBB2 amplicon core genes in breast cancer." (PMID 20158880, 2010). "Therefore, we suggest that the TNFAIP1/POLDIP2 SFGM could be used potentially as a new integrative indicator in breast cancer diagnosis, prognosis and treatment monitoring." (PMID 20158880, 2010). "We produced correlation tables that included both the genes of the TNFAIP1/POLDIP2 SFGM and the ERBB2 CR and their neighboring genes in the Uppsala and Stockholm breast cancer cohorts." (PMID 20158880, 2010). "Correlation matrix analysis with these 38 cell lines confirmed the clear co-regulatory pattern of the TNFAIP1/POLDIP2 SFGM, which was primarily identified in two breast cancer cohorts." (PMID 20158880, 2010). "Therefore, the TNFAIP1/POLDIP2 SFGM is also potentially regulated by STAT1 and Sp1 as well as stimulated by interferon-gamma in breast cancer cells." (PMID 20158880, 2010). "Preliminary data obtained in our pilot study (not shown) indicate that the TNFAIP1/POLDIP2 SFGM demonstrates stronger correlation pattern not with the ERBB2 breast cancer subtype but rather with luminal A and B subtypes." (PMID 20158880, 2010). "We characterize five genes (TMEM97, IFT20, TNFAIP1, POLDIP2 and TMEM199) organized in a CSAGA on 17q11.2 (we term this the TNFAIP1/POLDIP2 CSAGA) and demonstrate their strong and reproducible co-regulatory transcription pattern in breast cancer tumours." (PMID 20158880, 2010). "Therefore, the expression profiles of the genes of the TNFAIP1/POLDIP2 SFGM and the ERBB2 CR are correlated in breast cancer and this fact could probably be explained by co-amplification of their genomic regions." (PMID 20158880, 2010). "Similarly, in 38 breast cancer cell lines, the expression of the ERBB2 gene was significantly correlated with the expression of all the 5 members of the TNFAIP1/POLDIP2 SFGM, although the total number of observed significant correlations was less than for the breast cancer patients." (PMID 20158880, 2010).
breast carcinoma (continued). "Therefore, our survival analysis of the TNFAIP1/POLDIP2 SFGM and its "neighbouring genes" has revealed individual survival significant genes as well as significant gene pairs suggesting that the TNFAIP1/POLDIP2 SFGM is important for breast cancer prognosis." (PMID 20158880, 2010). "Moreover, we suggest that the co-regulatory pattern of the five member genes of the TNFAIP1/POLDIP2 SFGM could originally be established as the result of epigenetic modifications and/or transcriptional activation rather than by recurrent amplification in breast cancer cells." (PMID 20158880, 2010).
hepatocellular carcinoma (5 papers, 2016 to 2023). A malignant tumor that arises from hepatocytes. "Within the NF-kB signalling pathway in hepatocellular carcinoma, tumor necrosis factor, alpha induced protein 1 (TNFAIP1) was shown to interact with CK2β, promoting its ubiquitination and degradation, suppressing CK2β-dependent NF-kB activation." (PMID 34680478, 2021). "In addition, we demonstrated that downregulation of TNFAIP1 induced the expression of pro-inflammatory cytokines IL-6 and IL-8 in TNFα-stimulated hepatocellular carcinoma cells through the activation of p38/JNK MAPK pathway via blocking RhoB degradation." (PMID 33553178, 2021). "Studies have shown that TNFAIP1 mediates DNA replication, repair, and cell cycle regulation by interacting with PCNA, and it regulates hepatocellular carcinoma progression by interacting with CSNK2B." (PMID 37886961, 2023).
Alzheimer disease (3 papers, 2023 to 2024). A progressive, neurodegenerative disease characterized by loss of function and death of nerve cells in several areas of the brain leading to loss of cognitive function such as memory and language. "Early studies have found that TNFAIP1 is involved in the development of many tumors and is closely associated with the neurological disorder Alzheimer’s disease." (PMID 37239365, 2023). "Early studies found that TNFAIP1 is highly expressed at low pathogenic sites in Caenorhabditis elegans transgenic models of Alzheimer’s disease, and aberrant expression of the TNFAIP1 was detected in the brains of Alzheimer’s disease patients after death." (PMID 37239365, 2023). "TNFAIP1 upregulation was detected across the postmortem brain regions of Alzheimer’s disease (AD) cohorts and in the hippocampal neurons of APP/PS1 mice, suggesting its potential involvement in the pathogenesis of cognitive impairment." (PMID 38102610, 2023). "TNFAIP1 and p-TNFAIP1 (phosphorylation of TNFAIP1-Ser280 site) are upregulated in the cerebral cortex and hippocampal neurons of APP/PS1 double transgenic mice, suggesting a close relationship between TNFAIP1 and Alzheimer’s disease pathogenesis." (PMID 37239365, 2023).
colorectal cancer (3 papers, 2019 to 2024). A primary or metastatic malignant neoplasm that affects the colon or rectum. "Consistent with the favorable effects of TNFAIP1 on caspase 1/3/7 activity in macrophages or colorectal cancer cells, we found that TNFAIP1 promoted caspase-3 cleavage and subsequent generation of the N-terminal fragment of GSDME both in vitro and in vivo." (PMID 38102610, 2023). "Consequently, the degradation of EHMT2 reduces H3K9 dimethylation in the TNFAIP1 promoter region, leading to the upregulation of TNFAIP1 and apoptosis of colorectal cancer cells." (PMID 39048965, 2024).
gastric cancer (3 papers, 2013 to 2023). A primary or metastatic malignant neoplasm involving the stomach. "In gastric cancer, TNFAIP1 overexpression induced by miR-372 knockdown promoted cell apoptosis by regulating the NF-κB signaling pathway." (PMID 34972816, 2022). "The mRNA levels of TNFAIP1 in the gastric cancer and normal gastric tissues were negatively correlated with the expression levels of miR-373 in these tissues." (PMID 24179536, 2013).
osteosarcoma (3 papers, 2021 to 2022). A usually aggressive malignant bone-forming mesenchymal neoplasm, predominantly affecting adolescents and young adults. "Similarly, miR‐15a inhibits the proliferation of osteosarcoma cells, and this is thought to be through the downregulation of tumor necrosis factor α‐induced protein 1 (TNFAIP1) expression." (PMID 34785791, 2022). "TNFAIP1 could promote proliferation by upregulating caspase-3 and downregulating NF-κB and MMP2 in osteosarcoma cells." (PMID 34344926, 2021).
cervical carcinoma (2 papers, 2018 to 2021). A carcinoma arising from either the exocervical squamous epithelium or the endocervical glandular epithelium. "TNFAIP1 is frequently downregulated in uterine cancer tissues, and upregulation of TNFAIP1 expression inhibits tumorigenicity and cell growth in human cervical carcinoma (HeLa) and endometrial carcinoma cell line." (PMID 34001146, 2021). "We examined several well-known target genes of miR-224, such as Smad4, caspase 3, and TNFAIP1 and found no change in amiodarone-reduced miR-224 cells in a human papillomavirus (HPV)-infected cervical carcinoma cell line, HeLa cells." (PMID 29568365, 2018).
non-small cell lung carcinoma (2 papers, 2017 to 2021). A group of at least three distinct histological types of lung cancer, including non-small cell squamous cell carcinoma, adenocarcinoma, and large cell carcinoma. "Several microRNAs have been described to negatively regulate TNFAIP1 in a large number of tumors, confirming its pivotal role of tumor suppressor: miR-372 and miR-373 in gastric carcinoma, miR-224 and miR-424 in non-small cell lung cancer (NSCLC), miR-181a in pancreatic cancer." (PMID 34001146, 2021).
autism (1 paper, 2022). Persistent deficits in social interaction and communication and interaction as well as a markedly restricted repertoire of activity and interest as well as repetitive patterns of behavior. "Our predictions highlight the peculiar oligomerization properties of the members of Cluster 6 (KCTD10, KCTD13, and TNFAIP1), which are involved in important neurological pathologies including autism." (PMID 36362127, 2022).
cognitive decline (1 paper, 2023). "In summary, our findings demonstrated that inhibiting TNFAIP1-mediated degradation of SNAP25 might be a promising therapeutic approach for mitigating postoperative cognitive decline." (PMID 38102610, 2023).
cognitive disorders (1 paper, 2023). A disease affects cognitive processes. "Functional investigations further revealed that neuron-specific inhibition of TNFAIP1 alleviated postoperative cognitive disorders by intensifying PINK1/Parkin-dependent mitophagy and suppressing caspase-3/GSDME-dependent pyroptosis." (PMID 38102610, 2023). "Taken together, these findings support the idea that TNFAIP1 silencing mitigates postoperative cognitive impairment, intensifies PINK1/Parkin-mediated mitophagy and restrains caspase-3/GSDME-mediated pyroptosis by stimulating SNAP25 protein expression." (PMID 38102610, 2023). "Since we employed male animals in our study to reduce potential impact of estrogen and progesterone on cognitive ability in females, the effects of TNFAIP1 on surgery-induced cognitive impairment in female mice are not known." (PMID 38102610, 2023).
colon cancer (1 paper, 2022). "Subsequently, EHMT2 downregulation by propionate-induced tumor necrosis factor α-induced protein 1 (TNFAIP1) expression by reducing H3K9me2 levels to promote colon cancer apoptosis." (PMID 34972816, 2022).
ischemia (1 paper, 2023). A hypoperfusion of the BLOOD through an organ or tissue caused by a PATHOLOGIC CONSTRICTION or obstruction of its BLOOD VESSELS, or an absence of BLOOD CIRCULATION. "Conversely, TNFAIP1 silencing blocks the detrimental effects of these pro-inflammatory cytokines on PC12 cells and myocardium subjected to ischemia/reperfusion injury." (PMID 38102610, 2023).
lung adenocarcinoma (1 paper, 2020). A carcinoma that arises from the lung and is characterized by the presence of malignant glandular epithelial cells. "TNFAIP1 was overexpressed in both lung adenocarcinoma (upper) and squamous cell carcinoma tissues (lower) compared with adjacent normal tissues." (PMID 32327643, 2020).
medulloblastoma (1 paper, 2018). A malignant, invasive embryonal neoplasm arising from the cerebellum. "Among the 25 human KCTD family members, several have been linked to human cancers, including KCTD8, KCTD12, TNFAIP1 and most notably KCTD11/Ren/KCASH1, a reported tumor suppressor in medulloblastoma, possibly by suppressing Hedgehog signaling." (PMID 30142151, 2018).
microcephaly (1 paper, 2023). A congenital or acquired developmental disorder in which the circumference of the head is smaller than normal for the person's age and sex. "Tnfaip1 mutant embryos showed significant developmental delays as well as microcephaly and microphthalmia." (PMID 37239365, 2023).
parasitic infection (1 paper, 2020). "Genetic variants of interest identified in several immune related genes for all the antibody response and parasitic infection traits: IBDV (TOLLIP, ANGPTL5, BCL9, THEMIS2), MDV (GRM7), SG (MAP3K21), Eimeria (TOM1L1), and cestodes (TNFAIP1, ATG9A, NOS2)." (PMID 33193617, 2020).
tongue squamous cell carcinoma (1 paper, 2021). A squamous cell carcinoma that arises from the tongue. "Dataset-based analysis of cancer versus normal samples showed that TNFAIP1 expression was increased with fold changes of 2.230 and 2.190 in 31 cases of tongue squamous cell carcinoma tissues and 15 cases of tongue carcinoma." (PMID 34344926, 2021).